CXCL8 (C-X-C motif chemokine ligand 8)
Diseases named in the same sentence as CXCL8 in open-access papers (continued):
Sharing a sentence is not in itself a finding about the gene and the disease.
colon carcinoma (continued). "In summary, we found that shikonin suppresses colon cancer cell proliferation and migration through cellular experiments and identified eight genes (CCNB3, IL-1α, CXCL8, CDKN2A, MYC, IGFBP3, SQSTM1, and GADD45G) associated with cell senescence through systematic bioinformatics analysis." (PMID 39188951, 2024). "In addition, we detected CXCL8 from 10 pairs of colon cancer tissues and adjacent normal mucosa by RT-qPCR and found the similar results (t = 3.312, p = 0.0091)." (PMID 36358719, 2022). "Moreover, our previous studies and existing evidence suggested that CXCL8/CXCR1/2 is an important signal to promote liver metastasis of colon cancer." (PMID 36358719, 2022). "Furthermore, CXCL8 has also been found to promote the interaction between CSCs and mesenchymal stem cells (MSCs) to further enlarging the population of CSCs in colon cancer." (PMID 35372515, 2022). "The results suggest that the expression of CXCL8 or LSECtin in colon cancer is significantly positively related with the infiltration of CD8+ T lymphocytes, DC cells, macrophages, and neutrophils, which is a key factor affecting the therapeutic efficacy of ICIs." (PMID 36358719, 2022). "According to the results of DEGs interaction network and survival analysis, CXCL8 may be critical in the development and prognosis of colon cancer." (PMID 35922850, 2022). "CXCL8 RNAi-2 can significantly inhibit the proliferation and invasion of colon cancer cells." (PMID 36358719, 2022). "Interestingly, compared to TCGA normal and GTEx data, CXCL8 was substantially expressed in colon cancer patients." (PMID 35922850, 2022). "CXCL8 is overexpressed in many solid tumors, including lung, esophageal, breast, and colon tumors." (PMID 36072669, 2022). "IL-8 (also called CXCL8) mRNA expression was higher in colon cancer compared to para-cancer tissue." (PMID 35365616, 2022). "In this study, we analyzed the correlation between CXCL8 and LSECtin through the cancer genome atlas (TCGA) and gene expression omnibus (GEO) public data resources and explored the potential role of the CXCL8 or LSECtin in the immune microenvironment modulation of colon cancer." (PMID 36358719, 2022). "Studies have shown that CXCL8 is closely related to the immune cells infiltration in colon cancer." (PMID 36358719, 2022). "Furthermore, the findings from this study suggest that the prognostic influence of stromal CXCL8 was potentiated in patients with right‐sided colonic tumours." (PMID 35879507, 2022). "In conclusion, our experimental evidence confirmed that AC may suppress the growth and liver metastasis in colon cancer by regulating EMT via the CXCL8/CXCR2 axis and PI3K/AKT/mTOR signaling pathway." (PMID 35922850, 2022). "As such, interleukin (IL)-8 (CXCL8) signaling preserves the angiogenic phenotype in HIF1-α-deficient colon cancer cells, indicating a critical role of IL-8 in tumor-associated angiogenesis, independent of VEGF." (PMID 33352897, 2020). "CCL2 and CXCL8 induces epithelial-mesenchymal transition in colon cancer and bladder cancer." (PMID 31488217, 2019). "An important driver of chemokine gradients in the tumor microenvironment are cancer cells under aerobic glycolysis, which produce lactic acid that activates NF-κB and induces CXCL8 expression in vascular endothelial cells, resulting in angiogenesis in breast and colon cancer." (PMID 30800123, 2019). "Notably, IL17+ regulatory T cells can express CXCL8 in human colon cancer microenvironment, thus promoting inflammation and cancer cell dissemination." (PMID 30591657, 2018). "Increased expression of CXCL8 and its receptor CXCR2 on tumors and in the tumor microenvironment are associated with increased tumor growth, angiogenesis, and metastatic potential of colon cancer cells (52, –, 54)." (PMID 28717003, 2017).
colon carcinoma (continued). "To verify whether shikonin should potentially induce cell senescence in colon cancer cells by downregulating the expression of CDKN2A and CXCL8, we used a SA-β-Gal staining experiment to detect the senescent cells in the colon cancer cells that were treated with shikonin." (PMID 39188951, 2024). "Therefore, CXCL8 is a key factor of ICIs primary resistance in colon cancer." (PMID 36358719, 2022). "In addition, the area under the curve (AUC) value for CXCL8 was 0.7212 (95% confidence interval: 0.6777 to 0.7647, p < 0.0001), which means that CXCL8 could be regarded as a better prognostic biomarker for colon cancer patients." (PMID 35922850, 2022). "By constructing an interaction network of CXCs, CXCRs, intestinal flora, and human diseases, we found that there could be a possible association between CXCL8, Fusobacterium nucleatum, and human diseases (including inflammatory bowel disease (IBD) and colon cancer)." (PMID 34439306, 2021). "Moreover, P2Y6 activation increased CXCL8 secretion in the colonic tumor cell line Caco-2/15." (PMID 29541027, 2018). "Combining the expression trends of these genes in colon cancer and after aspirin treatment, we found that aspirin further upregulated NOX4, CXCL8, CXCL5, LIF, GDF15, and MMP13, while stimulated inhibition of IL2, NCF1, and PTGS1." (PMID 41425852, 2025). "In the microenvironment of colon cancer, CXCL8 and its receptor CXCR2 can promote the development and metastasis of colon cancer cells." (PMID 40131539, 2025). "In colon cancer cells, SKAP1 increased the expression of C‐X‐C motif chemokine ligand 8 (CXCL8) via nuclear factor of activated T cells c1 (NFATc1)." (PMID 39269257, 2024). "Consistently, treatment with the NFAT inhibitory peptide VIVIT almost completely abolished SKAP1‐induced CXCL8 expression, suggesting that SKAP1 dependents on NFATc1 to increase CXCL8 expression in colon cancer cells." (PMID 39269257, 2024). "CXCL8 up-regulated LSECtin through AKT signal and promoted the proliferation and invasion ability of colon cancer." (PMID 36358719, 2022). "It was reported that the expression of CXCL4 in colon cancer seems to counterbalance the angiogenic effects of both VEGF and CXCL8." (PMID 29850390, 2018). "Furthermore, qRT-PCR experimental results further confirmed that compared with normal colon epithelial cells, the expression levels of CCL22, CXCL1, CXCL8, and CXCL11 were upregulated in colon cancer cells." (PMID 38791448, 2024). "Based on these observations, we hypothesized that CXCL8 and CDKN2A are key regulators of cell senescence in HT29 and HCT116 colon cancer cells by shikonin." (PMID 39188951, 2024). "Based on our observations, we hypothesize that shikonin might play a pivotal role in inducing cellular senescence in colon cancer cells by suppressing the expression of CXCL8 and CDKN2A, ultimately leading to the inhibition of colon cancer development." (PMID 39188951, 2024). "Collectively, these results suggest that shikonin inhibits colon cancer development by downregulating the expression of CDKN2A and CXCL8, which may be involved in cellular senescence." (PMID 39188951, 2024). "Based on these findings, we propose that shikonin may induce senescence in colon cancer cells and inhibit colon cancer progression by downregulating CDKN2A and CXCL8." (PMID 39188951, 2024). "NFATc1 knockdown significantly decreased CXCL8 levels in the supernatants of colon cancer cells, whereas SKAP1 overexpression failed to significantly increase CXCL8 levels after NFATc1 knockdown." (PMID 39269257, 2024). "Referring to CXCL8 analysis methods, we found that all of the results from TCGA data, TCGA and GTEX integrated data and GSE110225 data indicated that the expression of LSECtin in colon cancer tissues was significantly lower than that in normal mucosa tissues." (PMID 36358719, 2022).
colon carcinoma (continued). "The CXCL8/CXCR1/2 chemokine axis and PI3K/AKT signaling pathway mediated EMT progress might well be a critical mechanism of colon cancer liver metastasis." (PMID 35922850, 2022). "CXCL8 could up-regulate LSECtin through AKT signal and promoted the proliferation and invasion ability of colon cancer." (PMID 36358719, 2022). "Taken together, these results suggested that AC may down-regulate CXCL8/CXCR2 chemokine axis and suppressing the PI3K/Akt/mTOR pathway to inhibit the EMT process, thus acting on its anti-liver metastasis effect in colon cancer." (PMID 35922850, 2022). "Taken together, the AC serum effectively relieved the indicators of inflammation and down-regulating the expression of colon cancer biomarker CXCL8 as determined by bioinformatics analysis but has no impact on another pro-inflammatory chemokine IL6." (PMID 35922850, 2022). "In addition to CCL2, CXCR2 ligands including CXCL1, CXCL2, CXCL3, and CXCL8 produced by CRC cells and neutrophils themselves were found to be responsible for recruitment of CXCR2+ neutrophils/PMN-MDSCs to colon tumors." (PMID 31681563, 2019). "Given that anti‐CXCL8 and anti‐NET therapies are currently being evaluated in clinical trials for the treatment of solid tumors, our study also proposes SKAP1 as a novel biomarker to identify patients with colon cancer who may benefit from these therapies." (PMID 39269257, 2024). "SKAP1 expression in colon cancer cells significantly promoted neutrophil infiltration and NET formation, which largely contributed to the tumor‐promoting effect of SKAP1, via nuclear factor of activated T cells c1 (NFATc1)‐dependent C‐X‐C motif chemokine ligand 8 (CXCL8) expression." (PMID 39269257, 2024). "In addition, CXCL8 has been shown to induce tumor related-EMT cascades through activation of the PI3K/AKT-ERK1/2 signaling pathway, which may also contribute to colon cancer cells resisting anoikis." (PMID 35922850, 2022). "In practice, several experimental evidences have documented that high expression of CXCL8 binds to receptors CXCR1 and CXCR2, mediates the transcriptional process of PI3K/Akt/mTOR signaling cascade, and promotes metastasis in multiple malignant tumors, specifically in colon cancer." (PMID 35922850, 2022). "CXCL8/AKT/LSECtin activation is positively related to the immune microenvironment regulation, and might be an important mechanism of ICIs primary drug resistance in colon cancer." (PMID 36358719, 2022). "Therefore, CXCL8/CXCR1/2 signal may regulate the expression of LSECtin and play an important role in the immune microenvironment regulation in colon cancer." (PMID 36358719, 2022). "However, whether blocking CXCL8/CXCR1/2 signal or LAG3/LSECtin can increase the efficacy of anti-PD-1/PD-L1 or anti-CTLA4 in patients with colon cancer is still lack of effective experimental verification." (PMID 36358719, 2022). "CXCL8, rather than other neutrophil‐related cytokines, has been identified as the key mediator of SKAP1‐induced interactions between colon cancer cells and neutrophils." (PMID 39269257, 2024). "In SW480 colon cancer cells, NF-κB activation by CPT was accompanied by secretion of the cytokine CXCL8, but not by up-regulation of the anti-apoptotic genes, cIAP2 or Bcl-XL." (PMID 25134433, 2014). "Colon cancer patients with upregulated NOX4, CXCL8, CXCL5, GDF15, or MMP13 may not benefit from aspirin chemoprophylaxis." (PMID 41425852, 2025).
glioma (218 papers, 2009 to 2026). A benign or malignant brain and spinal cord tumor that arises from glial cells (astrocytes, oligodendrocytes, ependymal cells). "Future studies incorporating multivariate models with comprehensive clinical, molecular, and immunological annotations are warranted to validate the independent prognostic role of CXCL8 and enhance its utility in glioma risk stratification." (PMID 41432874, 2025). "Together, these results highlight the key role of CXCL8 in shaping an immunosuppressive microenvironment in Grade 4 gliomas through its strong association with M2 macrophage-related functions." (PMID 41432874, 2025). "While CXCL8 has been previously implicated in glioma progression and immune infiltration, our study provides new insights by demonstrating that CXCL8 expression exhibits grade‐specific prognostic value, significant in Gr." (PMID 41432874, 2025). "Our study found that CXCL8 expression was associated with increased levels of immune cells, including macrophages and neutrophils, in gliomas." (PMID 41432874, 2025). "CXCL8 mRNA and protein levels were shown to be higher in grades II, III, and IV astrocytomas and anaplastic oligodendroglioma, indicating that CXCL8 expression is linked to glioma grade." (PMID 35269652, 2022). "The volcano plot revealed that glial cells in C5 derived from TDL upregulated expression of myelin-related genes (TYMP, CD9, MAG, and PMP22) and immune-related and inflammatory response-associated genes (IL1B and CXCL8) comparing to those from glioma." (PMID 36085357, 2022). "To understand the potential role of CXCL8 in shaping the immune microenvironment of high-grade gliomas, we investigated its association with various immune cell populations, aiming to elucidate possible mechanisms by which CXCL8 contributes to glioma progression." (PMID 41432874, 2025). "These patterns suggest that CXCL8-associated M2 macrophage infiltration may be particularly relevant to tumor progression and recurrence in Grade 4 gliomas." (PMID 41432874, 2025). "CXCL8, as a biomarker associated with M2 macrophage infiltration, could play a pivotal role in developing predictive systems for glioma treatment." (PMID 41432874, 2025). "The classification of WHO gliomas is also based in part on the IDH mutation status and 1p/19q codeletion; thus, we next analyzed the association of CXCL8 with these markers in Gr." (PMID 41432874, 2025). "Blocking CXCL8 or its receptors, CXCR1/2 has been shown to enhance anti-PD-1-mediated antitumor immunity, making CXCL8 a potential target for combination immunotherapy in gliomas." (PMID 41432874, 2025). "Elevated in cancers, such as breast, prostate and gliomas, CXCL8 correlates with advanced stages, poor survival, and therapy resistance." (PMID 40596054, 2025). "In glioma, LPS not only upregulates inflammatory mediators such as IL-8, CXCL8, and IL-1β to support tumorigenesis but also alters the immunophenotype of glioma cells and induces antitumor immunity via TLR4." (PMID 40444051, 2025). "Neutrophils are recruited to glioma inflammatory regions by chemokines such as CXCL1, CXCL2, CXCL3, CXCL5, CXCL6, IL-8 (CXCL8), and IL-1β, which are secreted by glioma cells." (PMID 41272822, 2025). "The gene expression level of both IL6 and CXCL8 was also downregulated in the CSMD1-high group compared to the CSMD1-low group in glioma cohorts." (PMID 38561856, 2024). "The TCGA database, CGGA database and clinical tissue samples were used to analyze CXCL8’s significance on prognosis for patients with glioma." (PMID 39488622, 2024). "High levels of CXCL8 can stimulate tumor angiogenesis or recruit immunosuppressive cells, while tumor-infiltrating neutrophils contribute to the progression of gliomas by regulating the HMGB1/RAGE/CXCL8 axis." (PMID 39488622, 2024). "In the present study, we sought to explore the key gene CXCL8 in methionine metabolism in gliomas and its potential role in angiogenesis." (PMID 39488622, 2024).
glioma (continued). "Meanwhile, we found that in the TCGA glioma cohort, CXCL8 expression was significantly higher in tumor samples than in normal samples." (PMID 39488622, 2024). "Angiogenesis is indispensable for maintaining the growth of gliomas, and we further explored the role of high CXCL8 expression during methionine metabolism on angiogenesis." (PMID 39488622, 2024). "Based on the critical role of CXCL8 in the metabolic remodelling of methionine in gliomas, we further used metabolomics targeting 100 amino acids to explore the changes in the metabolism of amino acids involved in the CXCL8–CXCR2 signaling axis." (PMID 39488622, 2024). "We previously found that CXCL8 was significantly upregulated in glioma cells with a methionine-restricted microenvironment." (PMID 39488622, 2024). "To further investigate the prognostic role of CXCL8 in gliomas, we downloaded the uniformly standardized brain glioma dataset from the UCSC database and analyzed the relationship between CXCL8 expression and survival prognosis." (PMID 39488622, 2024). "Glioma cells promote angiogenesis in methionine-restricted environments through the activation of CXCL8, compensating for nutrient deprivation, and possibly contributing to the failure of antiangiogenic therapy." (PMID 39488622, 2024). "DAMPs induces microglia in the area surrounding tumor necrosis to express IL-1β in a TLR-mediated manner, which induces glioma cells to release a range of cytokines such as CXCL8,CCL2, IL-1β and IL-6." (PMID 37700840, 2023). "Circulating neutrophils are recruited at the tumor site by CXCL8 produced by FasL triggering on glioma cells or by the Migration Inhibitory Factor (MIF) produced by glioma cancer stem cells." (PMID 35440701, 2022). "Glioma cells can secrete IL-8, MIF, and CXCL8, which induce neutrophil infiltration into the tumor site." (PMID 35920986, 2022). "CXCL8 was upregulated in GBM compared to diffuse astrocytoma and its expression levels were positively associated with progression and poor prognosis of glioma." (PMID 33803224, 2021). "CXCL8 is one of the most important chemokines in glioma and major regulator of this type of tumors pathogenesis." (PMID 34200145, 2021). "In human gliomas, CXCL8 is expressed and secreted at high levels by tumor cell both in vitro and in vivo." (PMID 32456359, 2020). "The proangiogenic activity of CXCL8 in gliomas is mainly related to CXCR2, which binds to all of the CXC ELR (+) chemokines." (PMID 32456359, 2020). "Accordingly, in PTEN-deficient GBM, the inhibition of STAT3 allows the expression of CXCL8 gene that promotes proliferation, invasion and spreading of glioma cells." (PMID 33066172, 2020). "IL-8 (CXCL8) is a pro-inflammatory chemokine produced by many cell types, including glioma, and can promote MDSC trafficking into the tumor microenvironment through the IL-8/IL-8R axis." (PMID 32391020, 2020). "IKK-inhibitors, BMS-345541 and TPCA-1, counteract cell proliferation, p65 nuclear translocation, and NF-κB-regulated CXCL8 gene expression in glioma cells." (PMID 30413032, 2018). "In addition, although direct evidence is limited, some studies have reported a correlation between tumor tissue and circulating CXCL8 levels in glioma patients, suggesting the potential of serum or CSF CXCL8 as a non-invasive biomarker." (PMID 41432874, 2025). "Recent studies have shown that CXCL8 expression is significantly upregulated in several cancers, including prostate cancer, colorectal cancer, head and neck squamous cell carcinoma, osteosarcoma, and glioma." (PMID 40596054, 2025). "Additionally, we examined the relationship between CXCL8 expression levels and glioma grade, as well as other clinical factors using the TCGA dataset." (PMID 41432874, 2025). "In addition to THBS1, our study also highlighted the importance of interleukin-8 (IL8, CXCL8) in glioma prognosis." (PMID 41432874, 2025).